DEF6 (DEF6 guanine nucleotide exchange factor)
Diseases named in the same sentence as DEF6 in open-access papers (continued):
Sharing a sentence is not in itself a finding about the gene and the disease.
cardiac hypertrophy (1 paper, 2023). "Then, DEF6 loss- and gain-of-function assays conducted both in vitro and in vivo revealed a deleterious regulatory role for DEF6 in pathological cardiac hypertrophy." (PMID 37524688, 2023). "As an upstream activator of MEK-ERK signaling, RAC1 has also been implicated in pathological cardiac hypertrophy and activated by DEF6 in the immune system and cell morphology modification." (PMID 37524688, 2023). "Our in vivo results revealed that DEF6 deficiency in mice alleviated transverse aortic constriction (TAC)-induced cardiac hypertrophy, fibrosis, dilation and dysfunction of left ventricle." (PMID 37524688, 2023). "This expression alteration implied that DEF6 might be implicated in pathological cardiac hypertrophy." (PMID 37524688, 2023). "To conclude, activation of Rac1-MEK-ERK signaling cascades is some of the mechanisms by which DEF6 accelerates the development of pathological cardiac hypertrophy." (PMID 37524688, 2023). "In conclusion, activation of Rac1 and MEK-ERK signaling cascades are some of the mechanisms by which DEF6 accelerates the development of pathological cardiac hypertrophy." (PMID 37524688, 2023). "Coinciding with the progression of cardiac hypertrophy and fibrosis, DEF6 overexpression remarkably enhanced the mRNA levels of the cardiac hypertrophic and fibrotic markers." (PMID 37524688, 2023). "Mechanistically, our research reveals that MAPK signaling participates in the effects of DEF6 on cardiac hypertrophy." (PMID 37524688, 2023). "In terms of mechanism, RAC1 and the MEK-ERK signaling cascade activation largely contributed to DEF6’s deleterious role in cardiac hypertrophy." (PMID 37524688, 2023). "All these data support that DEF6 contributes significantly to the development of pathological cardiac hypertrophy." (PMID 37524688, 2023). "The further rescue experiments using Rac1 inhibitor NSC23766 treatment and AdRac1(G12V) infection verified the requirement of Rac1 and MEK1/2-ERK1/2 activation for DEF6-mediated pathological cardiac hypertrophy." (PMID 37524688, 2023). "To further elucidate the impact of DEF6 on pathological cardiac hypertrophy, we initially determined the expression profile of DEF6 in ventricular samples of C57BL/6J wild-type (WT) mice processed with 1 week, 2 weeks, 4 weeks of TAC or sham surgery." (PMID 37524688, 2023). "In the end, western blot and rescue experiments using Rac1 inhibitor NSC23766 and the constitutively active mutant Rac1(G12V) verified the requirement of Rac1 and MEK1/2-ERK1/2 activation for DEF6-mediated pathological cardiac hypertrophy." (PMID 37524688, 2023). "Thus, we first demonstrated that the expression level of DEF6 is sensitive to the severity of pathological cardiac hypertrophy and DEF6 can remarkably exacerbates the pressure overload-induced cardiac hypertrophy." (PMID 37524688, 2023). "However, our current research first reveals the deleterious regulatory effects of DEF6 in cardiac hypertrophy through the Rac1-MEK1/2-ERK1/2 pathways." (PMID 37524688, 2023). "Our study substantiates that DEF6 acts as a deleterious regulator of cardiac hypertrophy by activating the Rac1 and MEK1/2-ERK1/2 signaling pathways, and suggests that DEF6 may be a potential treatment target for heart failure." (PMID 37524688, 2023). "However, DEF6 overexpression significantly deteriorated pressure overload-induced cardiac hypertrophy and pulmonary congestion, as shown by increments in HW, HW/BW, LW/BW, HW/TL, gross heart sizes, and cardiomyocyte cross-sectional area versus the control (AAV9-vector) group." (PMID 37524688, 2023). "Therefore, we hypothesized that DEF6 may regulate pathological cardiac hypertrophy through MEK-ERK signaling in an RCA1-dependent manner." (PMID 37524688, 2023).
cardiac hypertrophy (continued). "Numerous studies have supported the notion that many regulators of the immune system and cancers also participate in the regulation of cardiac hypertrophy, and considering that DEF6 is diffusely expressed in the heart, we sought to figure out whether DEF6 is implicated in cardiac hypertrophy." (PMID 37524688, 2023). "The effects of DEF6 on pathological cardiac hypertrophy, however, have not yet been fully characterized." (PMID 37524688, 2023). "In our mechanistic exploration, we found that DEF6 could directly interacted with Rac1 and enhance activities of Rac1 through increasing the binding ability of Rac1 with GTP in pathological cardiac hypertrophy." (PMID 37524688, 2023).
clear cell carcinoma (1 paper, 2016). "Surprisingly, high expression of DEF6 in clear cell carcinoma was significantly correlated to shorter overall survival (P = 0.001)." (PMID 27488395, 2016). "The level of DEF6 in A2780 (unknown histology subtype) and TOV-21G (clear cell carcinoma) was comparatively low among the six cells, however, they revealed a double-band pattern on the DEF6 region as similar to the oral carcinoma cells." (PMID 27488395, 2016).
endometrioid carcinoma (1 paper, 2016). "This indicated that DEF6 was preferentially overexpressed in ovarian serous and endometrioid carcinomas." (PMID 27488395, 2016). "Score 3 immunoexpression of DEF6 could be assessed in 52 % (39/75) and 64.3 % (18/28) of high-grade serous carcinoma and endometrioid carcinoma, respectively." (PMID 27488395, 2016). "Strong expression of DEF6 was observed in high-grade serous carcinoma and endometrioid carcinoma." (PMID 27488395, 2016).
esophageal cancer (1 paper, 2022). A primary or metastatic malignant neoplasm involving the esophagus. "Among solid tumors, the level of DEF6 expression was highest in head and neck cancer, esophageal cancer, and pancreatic cancer cell lines." (PMID 36686789, 2022).
joint disease (1 paper, 2020). "In disease settings, Def6 deficient DO11.10 mice on the Balb/c background with TCR activation developed a RA-like joint disease with bone erosion." (PMID 33373293, 2020). "Def6 deficient mice crossed with TCR transgenic DO11.10 mice develop RA-like joint disease with bone erosion." (PMID 33373293, 2020).
kidney cancer (1 paper, 2022). Primary or metastatic malignant neoplasm involving the kidney. "Finally, we analyzed trends in the levels of DEF6 expression in cancer cell lines, which were lowest in kidney cancer, neuroblastoma, and liposarcoma cell lines and highest in leukemia, myeloma, and lymphoma cell lines." (PMID 36686789, 2022).
melanoma (1 paper, 2022). A malignant, usually aggressive tumor composed of atypical, neoplastic melanocytes. "The results revealed that the overall frequency of DEF6 was relatively high in cancers and dominated by “copy number mutations”, with the highest value being found in melanoma, at over 5%." (PMID 36686789, 2022).
osteoporosis (1 paper, 2020). A condition of reduced bone mass, with decreased cortical thickness and a decrease in the number and size of the trabeculae of cancellous bone (but normal chemical composition), resulting in increased fracture incidence. "The enhanced bone resorption in Def6-/- mice dominates, leading to osteoporosis." (PMID 33373293, 2020). "Lack of Def6 leads to suppressed type-I IFN response, which in turn promotes the differentiation of osteoclasts and osteoblasts, resulting in a high turn-over osteoporosis." (PMID 33373293, 2020).
ovarian clear cell cancer (1 paper, 2016). An invasive malignant neoplasm that arises from the ovary and is characterized by a predominance of clear and hobnail malignant epithelial cells. "More importantly, in ovarian clear cell carcinoma, high expression of DEF6 was associated with shorter overall survival as compared to low DEF6 expression (P = 0.001)." (PMID 27488395, 2016). "Our study is the first report on the prognostic impact of DEF6 overexpression in early-stage ovarian clear cell carcinomas, however in-depth investigations are necessary." (PMID 27488395, 2016). "Therefore, our study suggests that patients of ovarian clear cell carcinoma with high DEF6 expression deserve a poor prognostic factor compared with other histological subtypes." (PMID 27488395, 2016). "DEF6 overexpression in early-stage ovarian clear cell carcinomas may have potential role as a poor prognostic factor." (PMID 27488395, 2016).
renal carcinoma (1 paper, 2025). A carcinoma arising from the epithelium of the renal parenchyma or the renal pelvis. "Nine intersecting genes were screened and used to construct a prognostic model, whereby seven key biomarkers—MXD3, PLCB2, CCDC88B, DEF6, IFNG, TBC1D10C, and PLEKHN1—were significantly influenced the prognosis of renal cancer." (PMID 41357186, 2025).
renal cell carcinoma (1 paper, 2016). "DEF6 may serve as a potential target for anti-angiogenic intervention in renal cell carcinoma." (PMID 27488395, 2016).
serous carcinoma (1 paper, 2016).
vasculitis (1 paper, 2021). "For example, abatacept in CTLA4 haploinsufficiency, LRBA and DEF6 deficiencies; tocilizumab in STAT3 GOF; JAK inhibitors in STAT3 and STAT1 GOF patients; alemtuzumab for CD25 deficiency; PIK3δ inhibitors for APDS or anti-TNFα therapy for vasculitis in ADA2 deficiency." (PMID 34447369, 2021).
cancer (7 papers, 2016 to 2023). A tumor composed of atypical neoplastic, often pleomorphic cells that invade other tissues. "As the association of DEF6 expression with cancer has been reported in only a few tumors, we performed an expression versus survival differential analysis." (PMID 36686789, 2022). "Overall, a high level of expression of DEF6 seems to be strongly associated with poor prognosis in patients, and studies in cancer are very limited." (PMID 36686789, 2022). "Since DEF6 deficiency is linked to several immunological disorders, we surmised that DEF6 may also be relevant to genes that regulate the immune system in cancer." (PMID 36686789, 2022). "In malignant tumors, DEF6 appears to be associated with a worse prognosis." (PMID 36686789, 2022). "Perhaps the DEF6 mutation is also responsible for the development of cancer." (PMID 36686789, 2022). "Differentially expressed in FDCP 6 homolog (DEF6) was reported to participate in immunity, bone remodeling, and cancers." (PMID 37524688, 2023). "We explored the genetic alterations of DEF6 in the TCGA pan-cancer datasets through the cBioPortal online resource." (PMID 36686789, 2022). "Further analysis showed that all of these dysregulated proteins had cancer-related associations, such as PDIA5, DEF6, MZB1, TXNDC5, YARS2, MGST1, and PIH1D1." (PMID 35958927, 2022). "To validate DEF6 as a predictor of cancer prognosis, we calculated the relationship between DEF6 expression and survival by univariate Cox survival analysis." (PMID 36686789, 2022). "There are only a few studies on the relationship between DEF6 expression and cancer, and it is believed that DEF6 expression contributes to cancer initiation and worse prognosis." (PMID 36686789, 2022). "It is necessary to explore the role of DEF6 expression in cancer through big data as well as bioinformatics." (PMID 36686789, 2022). "We first analyzed the RNA expression of DEF6 in cancer tissues compared with normal tissues using TCGA data." (PMID 36686789, 2022). "Overall, DEF6 expression is closely related to cancers and has the potential to act as a cancer biomarker." (PMID 36686789, 2022). "Gene modifications play a critical role in cancer development, and we evaluated the correlation between DEF6 expression and methylation-modified genes, including m6A, m5C, and m1A." (PMID 36686789, 2022). "As a result of cross-talk between cancer cells and immune cells, an environment is created that favors tumor growth and metastasis, which have a robust correlation between DEF6 expression in tumors." (PMID 36686789, 2022). "There is currently no pan-cancer analysis of DEF6, and we performed a systematic and comprehensive pan-cancer analysis of DEF6 in an attempt to reveal its role and function in cancer." (PMID 36686789, 2022). "Our results revealed that DEF6 is commonly aberrantly expressed in cancer and its expression is strongly correlated with survival prognosis in a variety of cancer types." (PMID 36686789, 2022). "Previous study on DEF6 mainly focused on its function in immunity and cancers." (PMID 37524688, 2023). "These pathways are closely related to cancer, and DEF6 expression may interact with or regulate these pathways." (PMID 36686789, 2022). "Previous findings suggest that DEF6 expression may play a key role in cancer, and using enrichment analysis we expect to elucidate the pathways and activities." (PMID 36686789, 2022). "CCL5, XCL1, XCL2, CCL17, CCL22, and CCL19 showed a positive correlation with DEF6 in most cancers, and DEF6 may function in regulating these chemokines in cancer." (PMID 36686789, 2022). "Using the TCGA and GTEx databases, we found aberrant expression profiles of DEF6 in cancer." (PMID 36686789, 2022). "There are few DEF6-related studies in cancer, and it is assumed that DEF6 is a proto-oncogene." (PMID 36686789, 2022). "Other enrichment analyses suggest that DEF6 may also be involved in purine metabolism, carbon metabolism, and multiple cancer pathways." (PMID 36686789, 2022).
cancer (continued). "Therefore, we conducted a comprehensive, multi-omic, pan-cancer analysis for DEF6, using several public databases, with the intention of revealing the character of DEF6 in cancers." (PMID 36686789, 2022). "In the enrichment analysis, DEF6 may have cross-talk with multiple cancer pathways and exert oncogenic or pro-cancer functions." (PMID 36686789, 2022). "Increased expression of DEF6 is correlated with the malignant behavior of various cancers." (PMID 27488395, 2016). "By analyzing patient survival data, we discovered that levels of DEF6 expression in COREAD were abnormally high and that patients with high levels of expression had considerably worse prognoses, indicating that DEF6 expression may have a unique role in promoting cancer in this disease." (PMID 36686789, 2022). "It was found that eight proteins (ADD2, DEF6, DOK3, ENO2, FMNL1, MICALL2, PARVG, and PSTPIP1) in KIRC cancer were more highly expressed in tumor tissues (100%), compared with normal tissues." (PMID 36428765, 2022). "This implies that DEF6 may have different functions in different cancers, and that in COREAD DEF6 may mainly play the role of oncogene." (PMID 36686789, 2022). "A systematic pan-cancer analysis of DEF6 would be valuable, and no pan-cancer analysis of DEF6 is available." (PMID 36686789, 2022). "Collectively, we uncover DEF6 as player in immune homeostasis ensuring availability of the checkpoint protein CTLA-4 at T-cell surface, identifying a potential target for autoimmune and/or cancer therapy." (PMID 31308374, 2019).
tumor (4 papers, 2016 to 2022). "Further, we calculated the correlation of DEF6 expression with multiple indicators of tumor heterogeneity." (PMID 36686789, 2022). "The results showed a close relationship between DEF6 expression and tumor immune genes and a robust correlation between DEF6 expression and immune infiltration score." (PMID 36686789, 2022). "We speculate that tumor cells with high levels of DEF6 expression may have greater metastatic capacity, but this needs to be verified in vitro." (PMID 36686789, 2022). "Atypically high levels of DEF6 expression may be a sign of carcinogenesis or tumor development in various malignancies." (PMID 36686789, 2022). "DEF6 expression may serve as an independent prognostic factor, and interacted positively with p16 toward high tumor stage and shorter survival." (PMID 27488395, 2016). "The association between tumor purity and immune cell infiltration may indicate that DEF6 is involved in immune recruitment, although this was not confirmed in the current study, necessitating further investigation by other researchers." (PMID 36686789, 2022). "The results showed us a significant correlation between the expression of DEF6 and MSI and tumor purity." (PMID 36686789, 2022).
immune diseases (3 papers, 2019 to 2022). "Previous studies have reported that DEF6 defects might cause immune diseases, and we speculate that mutations in DEF6 might also be present in tumors." (PMID 36686789, 2022). "In addition to the role for Def6 in immune diseases, recent GWAS study identifies DEF6 as a novel loci associated with BMD." (PMID 33373293, 2020).
heart disease (1 paper, 2023). "The highly enriched expression of DEF6 in the heart also implies that DEF6 may have important roles in heart disease." (PMID 37524688, 2023).
DEF6 also shares sentences with these, for which no sentence is quoted: clear cell renal cell carcinoma (1 paper); genetic disorders (1); head and neck cancer (1); heart failure (1); immunodeficiency syndrome (1); infection (1); inflammatory bowel disease (1); influenza (1); IPEX syndrome (1); leprosy (1); leukemia (1); liposarcoma (1); lymphoma (1); lymphopenia (1); myeloma (1); neuroblastoma (1); Obesity (1); oral carcinoma (1); oral squamous cell carcinoma (1); osteosarcoma (1); pancreatic cancer (1); pulmonary congestion (1).